IL10 (interleukin 10)
Diseases named in the same sentence as IL10 in open-access papers (continued):
Sharing a sentence is not in itself a finding about the gene and the disease.
infection (continued). "IL-10 and IFNγ CD4+ cells are important for a chronic, nonresolving infection status, and together with the elevated TNFα and IL-6 expression, these data fit well with the enhanced and prolonged inflammation in the colons of AOM/DSS-treated CerS4 LCK/Cre mice." (PMID 35163788, 2022). "The frequency of intracellular IL-10 CD4+ T-cell response in CHB, OBI, and resolved infections was higher than in HBV non-infected individuals (P < 0.01)." (PMID 35464946, 2022). "The degree of control of HCMV Merlin GFP infections by CD4 T cells in the absence of the anti-IL-10 block indicates T cell capacities that remain functional, despite the presence of induced IL-10 and pUL11." (PMID 36445084, 2022). "Non-productive and productive infection 100 days post-in vivo vaginal challenge induced distinct proteomic profiles which were characterized by further VEGF increase and IL-10 decrease in non-infected animals." (PMID 36145466, 2022). "In contrast, moM1 infection with virulent 22653/14 ASFV did not induce the release of either proinflammatory (IL-1α, IL-1β, IL-6, TNF-α) or anti-inflammatory (IL-10) or pro-Th1 (IL-12, IL-18) cytokines." (PMID 35215216, 2022). "Previous studies have shown that IL-10 is produced in the CNS in response to infection with NSV and that immunopathology and fatal paralysis are accelerated in the absence of IL-10." (PMID 36016413, 2022). "In the absence of maltol, challenge infection (NC group) with E. maxima increased (P < 0.05) the gene expression of IFN-γ (5.1 × 10−5-2.5 × 10−3) and IL-10 (9.1 × 10−5-1.2 × 10−3) in the distal jejunum compared to that of the CON group." (PMID 34095279, 2021). "After months to years without resolving infection, prolonged cellular immune response activation and production of pro-inflammatory cytokines eventually promote increased generation of IFN-γ/IL-10 co-producing Type 1 Regulatory T (Tr1) cells." (PMID 34827938, 2021). "PDGFRβ correlated negatively in BSIII–IV and positively in BSV–VI with several cytokines (IL-10, IL-12, IL-13, IL-2, IL-4 and TNF-α) but only in the absence of infection." (PMID 33723589, 2021). "Thus, we speculate that infection with H. diminuta creates a positive feedback loop whereby bacteria-derived butyrate and host-derived il-10 cooperate to drive the anti-colitic effect: absence of either negates the beneficial effect of infection with the helminth." (PMID 34517928, 2021). "Our data indicate that antiviral mechanisms are set during the peak of infection in the nasal epithelia with a timely induction of type I and III IFNs, ISGs and IL10 without exacerbation of pro-inflammatory cytokines." (PMID 34029358, 2021). "They found that serum IL-10 levels were increased at 72 h post-infection in infected B6 mice but not in infected NKSTAT3− and B6.Il10−/− mice, whereas the Lm burdens in the liver and spleen of NKSTAT3− and B6.Il10−/− mice were significantly reduced." (PMID 35053151, 2021). "It is worth noting that IL-17/IL-10 ratios were based on cytokine levels of C-TIM and dC-TIM, in the absence of infection." (PMID 35059328, 2021). "Untreated animals showed elevated levels of IL-6 and IL-10 but not IL-1β and TNF-α, in their lungs 4 days after the infection." (PMID 34648602, 2021). "IL-10, a Th2 cytokine promotes the VL infection in BALB/c at 8 weeks post-infection (Nylén and Gautam, 2010) while C57BL/6 mice did not upregulate IL-10 level." (PMID 33680991, 2021). "With the increased infection time, IL-1β and TNF levels did not consistently increase at 6 h postinfection compared to 3 h, whereas IL-6 and IL-10 did." (PMID 33664232, 2021). "Hepatic leukocytes from TgAlbCre-IL10-/- mice produced the highest levels of NO and IFN-γ, while the levels of IL-6, TNF and MIF were increased upon infection but not different between the groups." (PMID 32012211, 2020). "As such, infection with IAV (strain PR/08) induces secretion of IL-6, IL-8, MIP-1, RANTES, MCP-1, IL-10, and IFN-β, but neither IFN-α nor IFN-γ." (PMID 33255985, 2020).
infection (continued). "However, the expression of IL-10 and TNF-α in the gastric mucosa was positively correlated with the HbA1c levels, suggesting that inflammatory and anti-inflammatory markers released in the gastric mucosa during infection by H. pylori may be involved in the disturbance of glucose metabolism." (PMID 33013895, 2020). "Among SAH patients who developed any kind of infection, those with CVS or chronic shunt-dependent hydrocephalus had higher serum IL-10 levels compared to those who did not develop these complications." (PMID 32106601, 2020). "Infection resulted in an increase in antigen-specific cell proliferation, IFN-γ and IL-10 production by PBMC, but not IL-4 or IL-17A." (PMID 32487248, 2020). "On the other hand, there was no distinct trend between infection with CVI988 and vvRB1B and the expression of cytokines and chemokines, such as IL-10, IFN-γ, STAT1, IRF1, CCL19, and CCL26." (PMID 32210095, 2020). "Yet, between 38–48 days post infection, all tested pro-inflammatory cytokines (IFN-γ, TNF, IL-6 and MIF) increased or remained high in TgAlbCre-IL10-/- mice, but not in the other strains." (PMID 32012211, 2020). "Because we observed that intermediate monocytes express more TLR2 and TLR4 than classical and non-classical monocytes after infection with leishmania, we analyzed the frequency of cells expressing TNF and IL-10 on monocyte subsets expressing TLR2 and TLR4." (PMID 31119102, 2019). "The high levels of the regulatory IL-10 and the lower levels of proinflammatory TNF-α released by the B. abortus-PMN infected Mφs, at the initial stages of the infection, suggested a non-phlogistic phagocytosis mechanism." (PMID 31134082, 2019). "Depletion of macrophages did not significantly affect mRNA levels of IL-10, TNF-α, or IL-23p19 during infection." (PMID 31455692, 2019). "OO extract induced IL-10+/MHC II+ neutrophils in vitro; conversely, in grass-fed cattle maintained on pasture with repeated natural re-infections, and thus harboring chronic OO-infections, MHC II+ neutrophils failed to produce IL-10." (PMID 31889109, 2019). "Anti-Brucella antibodies abrogated the production of IL-6, IL-10, and IL-12 but did not affect the levels of IFN-γ at later stages of infection in PMNd-Br mice." (PMID 30804100, 2019). "On average 2.1 and 3.2 times more IFNG were produced by bMDM treated with IL10 siRNA rather than NTC siRNA during AF2122/97 and G18 infection, respectively." (PMID 31527895, 2019). "Mice administered binge alcohol 0.5 or 3 h prior to infection did not exhibit a significant difference in GM-CSF, TNF-α, IL-12/p40 or IL-10 concentrations in lung tissue homogenates." (PMID 31821337, 2019). "Uroepithelial cell-monocyte cocultures exhibited a 7-fold increase in IL-10 at 5 h after infection with MC4100/pflhDC and a 4-fold increase for other infections (on average) versus noninfected controls." (PMID 31776239, 2019). "It would be very useful to understand whether patients that suffered from infection-associated IUFD, in particular induced by gram-negative infections, had abnormalities in their IL-10 profile or whether B cells from these patients were unable to produce IL-10." (PMID 31249364, 2019). "Levels of IL‐10 produced in response to PHA were significantly higher at baseline compared to levels after 4 MDAs, regardless of infection status." (PMID 29604074, 2018). "During early infections [2 hours post infection (hpi) and 24 hpi], upregulation of IFN-β, TNF-α, IL1β, and IL-6 cytokines, with little to no IL-10, was observed in DENV-infected primary human macrophages, despite ADE." (PMID 29740424, 2018). "Infection of DCs with Rift Valley Fever virus (RVFV) induces the expression of TNF-α, IL-6, and IL-10 but not IL-8, IL-19, or IL-1β17." (PMID 30401896, 2018). "Published data shows that a cell-extrinsic increase in KLRG1 is unlikely to be secondary to reduced IL-10 production in Il27ra-/- mice, as Il10-/- and Il10r-/- mice show no (or a very marginal) upregulation of KLRG1 upon infection." (PMID 30044874, 2018).
infection (continued). "However, whether enhanced IL-10 signaling exhibits neuroprotective properties by preventing an excessive inflammatory response and/or accounts for reduced antiviral immunity during early infection has not yet been elucidated in TMEV-infected SJL mice." (PMID 29666403, 2018). "A comparative analysis of the secreted cytokines profile upon monocytes and neutrophils depletion suggested a protective role against infection for IL-2, IFN-γ, and TNF-α from macrophages, while IL-10 secretion seems not to be affected." (PMID 30197647, 2018). "Infection with ZIKV did not produce substantial alterations when compared to baseline levels prior, with the exception of TGFα, IL-1RA, IL-10, and MCP-1." (PMID 30469417, 2018). "Infection of MPI cells with HK bacteria resulted in the production of IL-6 and IL-1α from 24 h post-infection, in a MOI-dependent manner, while no IL-10 was detected (detection limit estimated to be ~60 pg/mL)." (PMID 29593716, 2018). "Whereas IFN-γ, IL-1β, IL-10, IL-12/IL-23p40, IL-17A, KC and MIG were not produced after infection or LPS-stimulation, elevated MCP-1 levels were measured only at 72–96 h (data not shown)." (PMID 28697801, 2017). "Without the amplification of immunoregulatory effects by IL-10, the expanded MDSC population is unable to reduce disease severity or aid in the resolution of infection." (PMID 28270815, 2017). "It was observed that rTgHSP70 immunization did not alter the production of IL-2, IL-4, IL-6, IL-10, IL-17a, IFN-γ, nor TNF, although infection with T. gondii promotes the production of inflammatory cytokines IL-6, IFN-γ, and TNF in all groups of mice." (PMID 28487847, 2017). "Consistent with the ELISA data, IL-10 expression was significantly enhanced in the BCG-infected BMDCs, compared to the Mpg-infected BMDC, irrespective of the time after infection (about five-fold increase compared with Mpg-infected BMDCs at each time-point)." (PMID 29123166, 2017). "Interestingly, the absolute numbers of IL-10-producing CD4+ cells in infected TSLPR−/− mice were higher than those from WT mice on day 45, and this could be explained by the higher hepatosplenomegaly observed during the late stage of infection in TSLPR−/− mice." (PMID 28769924, 2017). "The increase of IL-10 is greater in HIV-infected than uninfected individuals and declines but does not return to baseline levels by 6-month post- infection." (PMID 28143443, 2017). "At 72 h upon i.p. infection with Lb, macrophages from both B6 and BALB/c mice expressed an inflammatory phenotype, by producing TNF-α, G-CSF, and NO, but not IL-10 in Lb-stimulated cultures." (PMID 29204144, 2017). "Multiple cytokines in RDPs, including TNF-α, IL-8, IP-10, MCP-1, MIP-1α, IL-1ra, IL-10, G-CSF, IFN-γ, IL-4 and IL-17, reached peak value in 4 to 5 weeks after infection, whereas only IP-10 and IL-13 in SPDs did so, and lack of TNF-α in SDPs." (PMID 27830756, 2016). "Further, GFP+ and GFP- iregDCs expressed similar levels of IL-10 and PDL1 regardless of infection status, while the stimDCs expressed very little of either." (PMID 26808628, 2016). "Other cytokines and chemokines, such as IL-1β, IL-10, IL-17, TNF-α, IFN-γ, RANTES, and EOTAXIN, were also upregulated in the serum upon infection, but to a relatively lesser extent (data not shown)." (PMID 27756321, 2016). "Control (mock infection) cells virtually exhibited no binding of either Ap1, CREB or NF-κB1 p50 to the il10 promoter." (PMID 26883107, 2016). "Absence of IL-10 slightly reduced Nos2 transcription, but it did not affect NO production by macrophages upon BTB 02-171 infection." (PMID 27849167, 2016). "Through multiple techniques, we demonstrate that IL-10, PDL1 and iregDC generation are not specifically dependent on direct infection or recognition of intracellular viral replication by the LCMV sensors TLR3 or MAVS." (PMID 26808628, 2016).
infection (continued). "In the univariate analysis, levels of LBP, IL-10, IL-6 and CRP significantly differed between patients who developed an infection and those who did not." (PMID 25613713, 2015). "The antiviral response to TOSV in the CNS appeared to be properly modulated by the IL-10-mediated anti-inflammatory counterpart and all TOSV-infected patients in our study group cleared the neuroinvasive infection without permanent damage." (PMID 26569288, 2015). "Although dermal CD4+ T cells from 1x pinnae recovered on day 1 after infection did not proliferate in response to SSAP, a proportion of them were positive for IL-10 compared to naive mice." (PMID 25974019, 2015). "In contrast, infection with SS1 strain, which lacks a functional T4SS, failed to upregulate IL-10 production and FoxP3 expression." (PMID 25807464, 2015). "In the univariate analysis, levels of LBP, IL-10, IL-6 and CRP were compared between patients with and without infection." (PMID 25613713, 2015). "Secretion of IL-10 and TNF-α induced by AO3 and AR39 infection was also the same (data not shown), while IL-6 secretion was higher for AR39 but only for one MOI and only at 35 °C." (PMID 26494400, 2015). "GSEA revealed that genes from the MyD88-mediated pathways (P = 0.019) and IL-6, IL-10 and G-CSF cytokine pathways (P = 0.033) are highly enriched during HN878 infection when compared to non-infected samples." (PMID 25790379, 2015). "In a longitudinal study comparing uninfected and P. falciparum infected women during pregnancy, the increase of IL-10 level during PAM was combined to increased IP-10 level and decreased RANTES level regardless of gestational age at the time of infection." (PMID 26385579, 2015). "IL-10 production was examined in BMDC cells stimulated with or without LPS, prior to infection with L. mexicana." (PMID 25255446, 2014). "IL-10 producing Tr1 cells can also be isolated and cloned from patients with chronic HCV infection, but not from patients who cleared the infection." (PMID 24465502, 2014). "In the LCMV model, the lack of IL-10 or a defect in IL-10 signaling improves CD8 T-cell responses and drastically enhances the control of the infection." (PMID 24987395, 2014). "The survival times as well as ALT, NO and IL-10 levels in WT- and TbKHC1 KO-infected mice were similar in SIGN-R1 KO and control mice, suggesting that in late infection TbKHC1 signaling no longer operates primarily through SIGN-R1." (PMID 24204274, 2013). "Intriguingly, ablation of IL-10 production and IL-10R1 expression did not lead to a marked increase in the frequencies or total numbers of effector CD4+T-bet+ T cells during infection." (PMID 23593003, 2013). "In summary, our data clearly indicate a non-redundant role of T cell and myeloid cell derived IL-10 in facilitating viral chronicity and T cell exhaustion after LCMV Clone 13 infection as opposed to DCs, which were so far proclaimed to exert this function." (PMID 24244162, 2013). "The production of the anti-inflammatory cytokine IL-10 was also increased in both DLN and footpads of mycobacteriophage D29 treated mice, as compared to non-treated mice at day 68 post-infection." (PMID 23638204, 2013). "The frequency of IL-10-producing MLN cDC and pDC was also evaluated and did not significantly change upon infection (data not shown)." (PMID 23937079, 2013). "Gastric epithelial MKN7 cells produced the pro-inflammatory cytokines IL-6 and IL-8, but not IL-1β, IL-10, IL-12p70 or TNF (data not shown), after infection with H. pylori J99." (PMID 22563496, 2012). "While IL-10R blockade did not change viral load in the lungs on day 4 post infection, it did lead to an increase in the total cell numbers in the lung and BAL on day 8, as seen in IL-10−/− mice." (PMID 22393401, 2012). "Conversely, infection of neonatal mice with the same weight-based dose of RSV resulted in an absence of IFNγ, coupled with increases in IL-4 and IL-10." (PMID 22792355, 2012).
infection (continued). "HCs were pretreated with or without IL-10, TGF-β, IL-4, IL-6, IFN-γ, and TNF-α prior to infection with HIV-1BaL." (PMID 23217137, 2012). "In accordance with the IL-10 expression in BMMΦs, IL10 transcription in the liver was induced by the infection but was not significantly influenced by IE1." (PMID 22952450, 2012). "Further evaluation of liver pathology and damage in the absence of IL-10 during this infection was performed using periodic acid Schiff stained (PAS) liver sections taken from uninfected and infected WT and IL-10−/− mice." (PMID 22880122, 2012). "In contrast to the expansion of IL-10-producing CD4+ T cells, the frequency of splenic Foxp3+ Treg did not increase during infection, but instead decreased as previously reported." (PMID 22911108, 2012). "We find significant difference between the two groups regarding cytokine production for TNF-α at 24 h post-infection, but not for TGF-β1 and IL-10." (PMID 22574191, 2012). "Similar to IFN-α response following TLR7 stimulation, the production of IL10 in response to TLR3, 7, 8 ligands or following infection with PR8 was not dependent on “in vivo” stimulation by sex hormones and/or Cortisol." (PMID 22768144, 2012). "The sub-dominant epitopes not only failed to elicit IFN-γ and in vivo cytotoxicity during infection, but they also did not stimulate TNF-α, IL-2 or IL-10 secretion by CD8+ T cells." (PMID 21779365, 2011). "Infection of both monocytes and macrophages with TCRV also resulted in the release of high levels of IL-6, IL-10 and TNF-α, while levels of IFN-α, IFN-β and IL-12 were not affected." (PMID 21572983, 2011). "The real-time RT-PCR also revealed that the changes on gene expression of IL-10, GNA13 and TLR3 are not significantly changed at these early time points even at 100 MOI infection." (PMID 22028943, 2011). "In contrast, Il-1β, and Il-10 mRNA levels were not significantly different across strains, though the levels of Il-6 mRNA was markedly increased in MDA5−/− mice following infection." (PMID 20107606, 2010). "The anti-inflammatory IL-10, reported to be reduced in PA508 infection in CFTR knockout mice, was not altered in our present study." (PMID 21118573, 2010). "After no significant modulation during the first 14 hrs post-infection, IL-10 and COX-2 were expressed at a maximum level around D3 after a steady increase notably for IL-10." (PMID 20076757, 2010). "It is worth noting that we did not observe any overt immunopathology in IL-10−/− mice during WNV infection, and surviving IL-10−/− mice appeared active and healthy at the end of our infection experiments." (PMID 19816558, 2009). "IL-10 production by CD19+ B cells was observed, on day 7 post-infection, only during PyL but not PyNL infection (results not shown)." (PMID 18401464, 2008). "Here we demonstrate that infection with LCMVClone13, but not with LCMVARM, resulted in a steady increase in the serum levels of the immuno-inhibitory cytokine, IL-10." (PMID 17570849, 2007). "The anti-inflammatory cytokine IL-10 was detected after infection of splenocytes from both strains of mice, with BALB/c producing a significantly higher amount of IL-10 as compared to C57BL/6, although dead bacteria did not induce much IL-10 from both." (PMID 16919160, 2006). "We have detected up-regulation of IL-10 in HUVEC, B cells and DCs after LV infection suggested possible immune suppression by LVs (data not shown)." (PMID 15518595, 2004). "In a previous study performed by our work group, we found that in pediatric patients with ALL and fever without apparent infection, the TNF-α and IL-6 proinflammatory mediators were increased as well as the IL-8 and MCP1 chemokines and the immunosuppressive IL-10 cytokine." (PMID 40868835, 2025). "However, in individuals with previous infection, vaccination reactivates CD4+ T cells with a distinct cytokine profile, producing IFN-γ and IL-10, different from those detected in subjects without previous infection." (PMID 40170841, 2025).